CCND1 (cyclin D1)
Diseases named in the same sentence as CCND1 in open-access papers (continued):
Sharing a sentence is not in itself a finding about the gene and the disease.
breast cancer (continued). "Cyclin D1 amplification and high expression, common oncogenic events in luminal tumors, are more frequent in luminal B than in luminal A breast cancers." (PMID 32210163, 2020). "The EGFR/ERK1/2 signaling cascade upregulates the expression of Egr-1 that in turn participates in the transcription of CTGF and cyclin D1, two genes that regulate breast cancer growth." (PMID 33117280, 2020). "Cyclin D1 is involved in tamoxifen resistance in breast cancer (BC) but how it is regulated is unclear." (PMID 33139730, 2020). "For example, the expression of PR showed in female breast cancer a continuous dependency on cytokeratin 8/18, cyclin D1, B cell lymphoma 2 (Bcl-2), and cyclin-dependent kinase inhibitor p21." (PMID 32188473, 2020). "Overexpression of miR-503 in breast cancer cell lines reduced cell proliferation through inducing G0/G1 cell cycle arrest by targeting CCND1." (PMID 31249473, 2019). "Cyclin D1 is essential for breast cancer formation by coupling with CDK 4/6 to promote cell cycling." (PMID 30897298, 2019). "Preclinical evidence demonstrated that the interruption of cyclin D1/CDK4/6/Rb axis in breast cancer encountered the disruption of cell cycle." (PMID 31777590, 2019). "Overexpression of its protein has been found in 50–70% of breast cancers whilst amplification of its corresponding gene, CCND1, has been shown in approximately 9–30% of cases." (PMID 30819233, 2019). "In our study, western blot analyses of MDA-MB-231 and HCC1806 breast cancer cells CSCs showed that Gomisin M2 downregulates the Wnt/β-catenin self-renewal pathway and cyclin D1 expression via GSK3β activation." (PMID 31612865, 2019). "Collectively, these findings suggest that AHR and GPER are involved in the CYP1B1 and cyclin D1 induction upon exposure to 3MC toward the growth responses observed in breast cancer cells and CAFs." (PMID 31370872, 2019). "We analyzed the sequenced invasive breast carcinoma cases/patients from cBioPortal and found that Myc and CCND1 were highly amplified at the DNA level in breast cancer." (PMID 31462314, 2019). "The SNP rs614367 is located in an intergenic region with multiple flanking genes, including CCND1, MYEOV, ORAOV1, FGF19, FGF4 and FGF3, all of which are potential breast cancer susceptibility genes." (PMID 30247654, 2019). "Evidence from work on MCF7 breast cancer cells suggests that the growth inhibitory effect of GSK3β inhibition results subsequent decrease in cyclin D1 expression." (PMID 30446846, 2019). "The interactions between T cell activation status and either BRCA1 or CCND1 expression were evaluated using Kaplan-Meier survival curves and multivariate Cox regression models in a public dataset with 1088 breast cancer patients." (PMID 31023256, 2019). "EP significantly reduces the expression of BCL-XL (P < 0.001), as well as that of Cyclin D1 (P < 0.05) and c-Myc (P < 0.001), which are signaling molecules involved in cell cycle progression and proliferation in breast cancer cells." (PMID 30837881, 2019). "A study conducted in 2007 reported that the expression of cyclin D1 protein was 40%, 12%, 52% and 58% in breast cancer, colon tumors, glioblastomas and melanomas." (PMID 31583003, 2019). "FAM3C up‐regulates YY1 to induce HSF1 expression, finally activating Akt‐Cyclin D1 pathway to promote the proliferation and migration of breast cancer cells." (PMID 30887707, 2019). "Here we demonstrated, in estrogen receptor α (ERα)-positive breast cancer cells, an androgen-dependent mechanism through which ligand-activated androgen receptor (AR) decreases estradiol-induced cyclin D1 protein, mRNA and gene promoter activity." (PMID 31684907, 2019). "For example, the lncRNA LINC01355 is transcribed from the 1p36 locus in humans and is a tumor suppressor in breast cancer—LINC01355 inhibits cyclin D1 (CCND1) expression." (PMID 31717266, 2019). "Cyclin D1 activates CDK4/6 which is a current target in the clinic for chemoresistant cases of breast cancer." (PMID 31106142, 2019).
breast cancer (continued). "In the present study we provide a mechanism by which ligand-activated AR, down-regulates estrogen-dependent MCF-7 human breast cancer cell proliferation by inhibiting the ability of E2/ERα signalling to direct transcription of the cyclin D1 gene promoter." (PMID 31684907, 2019). "Surprisingly, the data showed that baneh gum alone or in combination of doxorubicin significantly reduces the expression of Cyclin-D1 in breast cancer cell line." (PMID 32184861, 2019). "We tried to prove that the influence on the proliferation of breast cancer cells is due to activation of the AR and that the activated AR slows down the cell cycle by influencing the expression of the Cyclin D1 gene via histone modification." (PMID 31235695, 2019). "Further, CCND1 is highly overexpressed in FGFR1-amplified breast cancers and the co-amplification of these two genes correlates with poor patient outcome." (PMID 30914635, 2019). "The present study is the first demonstration that the low LPP1 activity in breast cancer cells leads to increased production of MMPs and cyclin D1/3 by transcriptional regulation through the AP-1 complex." (PMID 31534541, 2019). "Of note, all three ER+/HER2−/FGFR1-amplified breast cancer cell lines used herein also harbor CCND1 amplification." (PMID 30914635, 2019). "A recent study reported that cannabidiol-induced apoptosis of breast cancer cells by downregulation of mTOR and cyclin D1, and upregulation PPARγ." (PMID 31075907, 2019). "For instance, mice lacking cyclin D1 or CDK4, as well as mice expressing mutant cyclin D1 (incapable of activating CDK4/6) were resistant to breast cancer induced by the Erbb2/HER2 oncogene." (PMID 30959874, 2019). "Tissue sections including both invasive tumor and adjacent benign components from 21 breast cancer patients with high grade tumors were immunostained for K19, cyclin D1 and cyclin D3 and semiquantitatively scored for their immunoreactivity." (PMID 31601969, 2019). "Although CCND1 is well-established as a cancer driver gene, it seems that CCND1 is an ER-positive breast cancer marker." (PMID 31921621, 2019). "For instance, one such study showed that TIPE2 prevented the migration and invasion of breast cancer cells through inhibition of β-catenin, cyclin D1, c-Myc, and epithelial-to-mesenchymal transition (EMT)." (PMID 31817720, 2019). "It has been demonstrated that the overexpression of cyclin D1 is correlated with higher tumor grade in papillary thyroid carcinoma, breast cancer, renal cell carcinoma and prostate carcinoma." (PMID 31583003, 2019). "CCND1 amplification and overexpression are involved in breast cancer, lung cancer, melanoma and oral squamous cell carcinoma." (PMID 31632494, 2019). "Consistent with prior studies, cyclin D1 mRNA levels were increased in breast cancer compared with healthy breast tissue." (PMID 30718920, 2019). "The correlation between CCND1 expression levels and cellular proliferation in breast cancer cells has been also confirmed by CCND1 silencing experiments, indicating cyclin D1 as a potential therapeutic target for breast cancer." (PMID 31684907, 2019). "Genes up-regulated in MCF-7 cells (breast cancer) over-expressing a mutant K112E form of CCND1 gene." (PMID 31191821, 2019). "Globular adiponectin induces p27 but inhibits Cyclin D1 in breast cancer cell lines MCF7 and hepatic cancer cell line HepG2 along with caspase 3/7 activation and FasL expression." (PMID 31121868, 2019). "The allelic frequency of the CCND1 rs614367-T was higher in patients with breast cancer compared to control subjects resulting in a significantly positive OR associated with this allele (OR = 1.38, P = 0.032)." (PMID 31921621, 2019). "The levels of the MYC proto‐oncogene (MYC) and cyclin D1 (CCND1) were detected by western blotting and quantitative reverse transcription‐polymerase chain reaction in breast cancer cells with SIRT4 overexpression or depletion." (PMID 31573734, 2019).
breast cancer (continued). "Taken together, our data therefore reveal a new mechanism by which calcineurin inhibits cyclin D1 degradation by dephosphorylation of the T286 residue, facilitating cell cycle progression and robust cell growth in invasive breast cancer cells." (PMID 31484966, 2019). "Since many of the estrogen-induced genes that regulate breast cancer proliferation and progression are also regulated by hypoxia (Cyclin D1, WISP2, etc.), KDM4B serves to integrate two known drivers of breast cancer progression." (PMID 30759871, 2019). "G9a mRNA levels correlated with cyclin D1 mRNA levels in healthy breast tissue (R = 0.29, P = 0.003) and ERα+ breast cancer samples (R = 0.27, P = 8.07e-30)." (PMID 30718920, 2019). "Here, we aimed to determine if amplification of CCND1 can function as a molecular biomarker for long-term breast cancer survival and more generally to comprehensively characterise its prognostic and treatment predictive capacity." (PMID 30819233, 2019). "Use of cyclin D1 (CCND1) gene amplification as a breast cancer biomarker has been hampered by conflicting assessments of the relationship between cyclin D1 protein levels and patient survival." (PMID 30819233, 2019). "It is widely studied that phosphatidylinositol-3 kinase (PI3K)/AKT pathway is activated in a variety of malignancies, such as EC, breast cancer, and ovarian cancer, which leads to cell proliferation and growth by regulating the cyclin D1 level." (PMID 31001342, 2019). "CCND1 amplification has been reported in many cancers, including breast cancer, esophageal cancer, laryngeal, and lung cancers." (PMID 31324163, 2019). "The mechanism by which estrogens regulate cyclin D1 levels in hormone-responsive breast cancer cells is mainly transcriptional." (PMID 31684907, 2019). "Therefore, CCND1 is highly likely to be the gene that mediates rs614367 breast cancer susceptibility: variants in the enhancer region (either rs614367 or other functional variants) may be hypothesized to drive risk by disrupting E2F1/GATA3/MYC/TCF7L2/ZNF217 binding and affecting CCND1 expression." (PMID 30247654, 2019). "In breast cancer, cyclin D1 amplification and CDK4 copy gain are common in luminal and HER2-enriched subtypes but are rare in basal-like tumors with Rb loss or mutation and cyclin E1 amplification." (PMID 31632494, 2019). "In prostate cancer, breast cancer and squamous carcinoma cells, curcumin not only downregulated cyclin D1 mRNA expression, but also promoted cyclin D1 proteolysis to exert its antiproliferation activity." (PMID 31409760, 2019). "Biochemically, LINC01355 overexpression inhibits the expression of cyclin D1 in breast cancer cells." (PMID 31243265, 2019). "Overexpression of 4EBP1 drives proliferation of luminal breast cancer cells by mechanisms involving cell cycle regulators such as cyclin D1 and the cdk inhibitor p27." (PMID 31122207, 2019). "Further, Myc (encoding c-Myc) and CCND1 (encoding Cyclin D1), AXIN2, etc. as canonical Wnt signaling targets were highly amplified in breast cancers." (PMID 31462314, 2019). "Cyclin D1 was involved in the AKT–glycogen synthase kinase 3 β–β‐catenin–cyclin D1 signaling pathway that participated in the process of extracellular 5′‐nucleotidase (CD73) promotion of cell growth of human breast cancer." (PMID 30974047, 2019). "CCND1 stimulates the cell cycle in breast cancer by binding to cyclin-dependent kinase 4/6 (CDK4/6)." (PMID 31112577, 2019). "Progesterone-Receptor (PR) positivity is related with an enhanced response to breast cancer therapy, conversely cyclin D1 (CD1) is a retained marker of poor outcome." (PMID 31426542, 2019). "MiR-503 suppresses cell proliferation, migration and invasion via suppressing CCND1 expression in breast cancer and ESCC." (PMID 31340767, 2019). "Prodigiosin decreases the tumorigenic potential and expression of cyclin D1 in breast cancer cells by inhibiting the Wnt/β-catenin pathway." (PMID 31799196, 2019).
breast cancer (continued). "YY1 silencing blunted FAM3C‐ and TGFβ‐triggered activation of HSF1‐Akt‐Cyclin D1 pathway, and proliferation and migration of breast cancer cells." (PMID 30887707, 2019). "Further, TIPE2 was found to downregulate the expression of different proteins, such as β-catenin, cyclin D1, and c-Myc in breast cancer cells." (PMID 31817720, 2019). "The low LPP1 expression was associated with increased levels of MMPs, cyclin D1/D3, cFOS, cJUN, and FRA1 in breast cancer patients." (PMID 31534541, 2019). "Apparently androgens are offering a way to reduce the expression of cyclin D1 in breast cancer cells thereby retarding the cell cycle." (PMID 31235695, 2019). "Taken together, these results demonstrate that ivermectin treatment of canine mammary tumor cells triggers accumulation of cells in the G1 phase via the inactivation of cyclin D1 and CDK4." (PMID 31375107, 2019). "In this study, we evaluated the copy number of FOSL1, GSTP1,CCND1 in different subtypes of breast carcinomas, classified accordingto the status of hormone receptors, ER and PR, KI-67, and HER2 protein." (PMID 30816904, 2019). "More recently, increased expression levels for AIF1L were reported in cases of breast cancer and functionally related to increased proliferation rates via upregulation of cyclin D1." (PMID 30001384, 2018). "B-cell lymphoma-extra large (Bcl-xL) and cyclin D1, which mediate anti-apoptotic response and cell proliferation, respectively, are upregulated in breast cancer tissues that are resistant to genotoxic drug treatment." (PMID 29352223, 2018). "For example, activation of GSK3β induces apoptosis, accumulation of β-catenin and suppression of Cyclin D1 expression in human breast cancer cells." (PMID 29700285, 2018). "Deregulation of cyclin D1 has been reported to be observed in cancers including breast cancer and lung cancer cells." (PMID 30279365, 2018). "The expression of miR-17 was decreased in breast cancer cell line, and gene expression of Cyclin D1 decreased after lentiviral transduction of miR-17 to breast cancer cells." (PMID 29351283, 2018). "In breast tissue, the CDK4/cyclin D1 axis appears critical for cancer initiation, as demonstrated using animal models and analysis of human breast cancer specimens." (PMID 29669860, 2018). "We have previously demonstrated that MUC1-EGFR complexes are capable of localizing around and entering the nucleus, acting as a co-transcriptional activator of genes upregulated in breast cancer, such as cyclin D1." (PMID 29464085, 2018). "It is interesting to note that the mRNA levels of EIF2AK2 and ANXA1 were significantly higher while those of PGR and CCND1 were significantly lower in two ER-- breast cancer cell lines than in MCF-7 cells." (PMID 29416786, 2018). "Overexpression of cyclin D1 was tightly related to many types of cancer such as breast cancer, lung cancer, colon cancer, and prostate cancer." (PMID 30108651, 2018). "Very recently, cell cycle inhibitors have been shown to be beneficial in metastatic breast cancer patients when added to endocrine therapy, both in CCND1 amplified tumors as well as in unselected patients." (PMID 30041599, 2018). "Evaluating the expression of cell cycle proteins showed that cyclin D1 and cyclin E2 were significantly induced in breast cancer cells in which TAP was knocked down." (PMID 29435127, 2018). "SIX1, which has been reported to be involved in various cancer progressions and correlated with poor prognosis in breast cancer 30, acts as a tumour‐promoting factor by regulating c‐myc, cyclin‐D1 and cyclin‐A1." (PMID 29435409, 2018). "SOX2 was revealed to be amplified and overexpressed in gastric cancers, and depletion of SOX2 markedly inhibited cell proliferation and tumor growth in breast cancer through downregulating CCND1 and PARP27." (PMID 30108202, 2018). "The elevated levels of p21cip, p18 and decreased expression of cyclin D1 in ectopically expressed ERRβ breast cancer cell lines were observed." (PMID 29843638, 2018).
breast cancer (continued). "Only very recently, it was shown that AIF1L is highly expressed in conditions of breast cancer and correlates with proliferation behavior via modulation of cyclin-D1 levels." (PMID 30001384, 2018). "A recent study has demonstrated that the activity of the estrogen receptor α (ERα)-coupled BMI1 signature impacts p16INK4a and cyclin D1 status and correlates with the tumor molecular subtype and biologic behavior in breast cancer." (PMID 29685168, 2018). "Further, E2 is able to induce BCL-2 and CCND1 in breast cancer cells and they are downstream from AKT1." (PMID 29416771, 2018). "The clinical importance of CCND1 gene lies in the fact that 5–20% of breast cancer cases present with either amplified or deleted version of the gene." (PMID 30361291, 2018). "In this study, we have established the correlation between the expression of ERRβ and various cell cycle markers such as p21cip, p18 and cyclin D1 in breast cancer cells." (PMID 29843638, 2018). "Overexpression of cyclin D1, a driver of G1/S transition during cell cycle progression, has been observed in more than half of breast cancers." (PMID 29783777, 2018). "In breast cancer cells, SIRT6 expression was associated with increased expression of MMP, cyclin D1, and NFκB, and was involved in nuclear localization of β-catenin." (PMID 30524965, 2018). "Understanding the process of amplicon formation, an example of which we present here for the chr8:ZNF703/FGFR1 and chr11:CCND1 co-amplifications, will be important for our understanding of the origins of a subset of breast cancers." (PMID 30252041, 2018). "In human breast tumor tissues, mRNA levels of EIF2Ak2, USP18, DDX58, RBL2, STAT2, PGR, S1000A9, and CCND1 were significantly higher in ER+- than in ER--breast cancer tissues." (PMID 29416786, 2018). "The chr8:ZNF703/FGFR1 and chr11:CCND1 amplifications are amongst the most frequent in breast cancer, particularly in ER-positive breast tumours (19% and 28%, respectively, of amplifications in ER-positive tumours; 11% and 16%, respectively, of total cohort)." (PMID 30252041, 2018). "MiR-17 was shown to target the 3' UTR of Cyclin D1 gene in breast cancer cells with the highest score using bioinformatics analyses." (PMID 29351283, 2018). "Mechanistic analyses indicate that ERα directly targets ERRβ through estrogen response element and ERRβ also mediates cell cycle regulation through p18, p21cip and cyclin D1 in breast cancer cells." (PMID 29843638, 2018). "CDK4/6 activity is particularly relevant in ER positive breast cancers, given that the cyclin D1 gene CCND1 is regulated by ERα." (PMID 30148117, 2018). "CCND1 is over-expressed in a considerable portion of human malignancies such as breast and prostate cancer and it has been shown as a miRNA target in breast cancer cells and primary prostatic epithelial cells." (PMID 29703916, 2018). "We further performed immunohistochemical staining for ZEB1, Bcl-xL and cyclin D1 in an independent cohort of 139 cases of primary breast carcinoma." (PMID 29352223, 2018). "A majority of the cyclin D1-positive cells in breast cancer stroma display a fibroblastoid phenotype with their characteristic highly elongated nuclei." (PMID 29137220, 2017). "For immunostaining of cyclin D1 in human breast cancer specimens we have used clinical grade DAKO 3642 rabbit monoclonal antibody specific for the 36 kDa human cyclin D1." (PMID 29137220, 2017). "A cohort of 914 breast cancer specimens with available clinical outcome was stained for stromal cyclin D1 using immunofluorescence-immunohistochemistry." (PMID 29137220, 2017). "RANKL signaling also activates downstream signaling cascades such as NF-kB and cyclin D1, which are key pathways, involved in breast cancer development." (PMID 29088745, 2017).